POLG2 (DNA polymerase gamma 2, accessory subunit)
Description:
Accessory subunit of DNA polymerase gamma solely responsible for replication of mitochondrial DNA (mtDNA). Acts as an allosteric regulator of the holoenzyme activities. Enhances the polymerase activity and the processivity of POLG by increasing its interactions with the DNA template. Suppresses POLG exonucleolytic proofreading especially toward homopolymeric templates bearing mismatched termini. Binds to single-stranded DNA.
Synonyms: MTPOLB; HP55; MTDPS16; MTDPS16A; MTDPS16B; PEOA4; POLG-BETA; POLGB
Tractability: Small molecule: a structure with a bound ligand is known; it has a high-quality binding pocket. PROTAC: ubiquitination databases record sites on it.
Gene: Protein-coding gene on chromosome 17 (64,477,781 to 64,497,071, reverse strand). Ensembl gene ENSG00000256525.
Subcellular location: Mitochondrion; Mitochondrion matrix, mitochondrion nucleoid
Subcellular location (Human Protein Atlas): Mitochondria; Nuclear bodies
Pathways (Reactome):
DNA Replication: Strand-asynchronous mitochondrial DNA replication
Organelle biogenesis and maintenance: Transcriptional activation of mitochondrial biogenesis
Gene Ontology:
Molecular function: DNA polymerase binding; DNA polymerase processivity factor activity; double-stranded DNA binding; protein binding; DNA-directed DNA polymerase activity; identical protein binding
Biological process: DNA-templated DNA replication; mitochondrial DNA replication; positive regulation of DNA-directed DNA polymerase activity; DNA biosynthetic process
Cellular component: gamma DNA polymerase complex; mitochondrial matrix; mitochondrial nucleoid; mitochondrion
Genetic constraint (gnomAD): Loss-of-function variants: 27 observed, 32.22 expected, observed/expected ratio (o/e) 0.84, 90% interval 0.62 to 1.16. The upper end of that interval is the gene's LOEUF score, 1.16, which puts it in group 5 of 6, group 1 being the genes least tolerant of losing a copy. Missense variants: 425 observed, 444.32 expected, observed/expected ratio (o/e) 0.96, 90% interval 0.88 to 1.04. Synonymous variants: 176 observed, 177.05 expected, observed/expected ratio (o/e) 0.99, 90% interval 0.88 to 1.13.
Homologues: Orthologues: chimpanzee POLG2 (99% identical), macaque POLG2 (97% identical), dog POLG2 (87% identical), guinea pig POLG2 (82% identical), pig POLG2 (81% identical), rabbit POLG2 (81% identical), mouse Polg2 (73% identical), rat Polg2 (73% identical), tropical clawed frog polg2 (47% identical), zebrafish polg2 (40% identical), Drosophila melanogaster PolG2 (18% identical). Paralogues in human: GARS1 (22% identical).
Diseases named in the same sentence as POLG2 in open-access papers:
POLG2 is named in the same sentence as 43 diseases in open-access papers, as found by Europe PMC text mining. Sharing a sentence is not in itself a finding about the gene and the disease. The quoted sentences say what the papers report.
progressive external ophthalmoplegia (6 papers, 2019 to 2025). A mitochondrial myopathy characterized by slowly progressive paralysis of the levator palpebrae, orbicularis oculi, and extraocular muscles. "Among nuclear DNA-related cases, mutations in POLG and POLG2, which encode subunits of mitochondrial DNA polymerase γ, are particularly significant, causing conditions such as Alpers-Huttenlocher syndrome and progressive external ophthalmoplegia." (PMID 41453949, 2025). "Taken together, we provide evidence that the novel POLG2 variant leads to impaired mitochondrial integrity suggesting its pathogenicity for the mitochondrial phenotype (ataxia and progressive external ophthalmoplegia) in the present family." (PMID 37085601, 2024). "The first reported POLG2 case was documented in a patient with adult-onset autosomal dominant (ad) progressive external ophthalmoplegia (PEO) as well as COX-deficient muscle fibres and multiple deletions in the mtDNA." (PMID 31991853, 2020).
Ataxia (5 papers, 2017 to 2025). Ataxia refers to impaired coordination of voluntary muscle movement. "The clinical spectrum of heterozygous POLG2 mutations comprise cerebellar ataxia, seizures, peripheral neuropathy, CPEO, and other movement disorders (tremor, parkinsonism) in adulthood-onset and metabolic abnormalities and seizures in childhood-onset cases." (PMID 41245005, 2025). "We report two siblings with a heterozygous POLG2 variant exhibiting cerebellar ataxia and progressive ophthalmoplegia in one sibling and dysmetria of saccades in the other sibling." (PMID 37085601, 2024). "Other biallelic POLG2 mutations in two independent individuals have been linked to epilepsy and a combination of childhood-onset optic atrophy, cerebellar ataxia, peripheral neuropathy, psychiatric comorbidities, and premature ovarian failure, respectively." (PMID 37085601, 2024). "Similar to POLG-related disease, the clinical spectrum of heterozygous POLG2 mutations comprises cerebellar ataxia and PEO in adulthood-onset and metabolic abnormalities and seizures in childhood-onset cases." (PMID 37085601, 2024). "PD associated with GBA1, SNCA and RFC1 has been reported in north Karelia, where the author also diagnosed a family with POLG2-associated PD (POLG2-mutations have been observed also in ataxia patients in the region; all data are unpublished)." (PMID 37373667, 2023). "Autosomal dominant mutations in POLG2 have been shown to cause late-onset PEO with mtDNA deletions, but again, more complex phenotypes with ataxia, parkinsonism and neuropathy have been associated with POLG2 variants." (PMID 35160083, 2022). "The core features included progressive ophthalmoplegia and cerebellar ataxia; parkinsonism, neuropathy, cognitive decline, and seizures were also repeatedly found in adult-onset heterozygous POLG2-related disease." (PMID 37085601, 2024). "We therefore suggest to include POLG2 sequencing in the evaluation of ataxia and sensory neuropathy in adults, especially when it is accompanied by tremor or parkinsonism with white matter disease." (PMID 28078310, 2017). "Cerebellar ataxia can also occur in POLG2-related disease, which is very rare." (PMID 41245005, 2025). "Their clinical presentation was in line with the previously observed phenotype of POLG2-related disease, including PEO in the index patient and cerebellar ataxia in both siblings." (PMID 37085601, 2024). "Spinocerebellar ataxias due to repeat expansions and pathogenic variants in 188 ataxia genes, including POLG but not POLG2, were excluded prior to exome sequencing in the index patient and her affected brother." (PMID 37085601, 2024).
liver failure (4 papers, 2018 to 2024). A liver disease characterized by the liver losing or has lost all of its function. "As expected, biallelic POLG2 variants can lead to a more severe phenotype with early-onset liver failure and death, referred to as mtDNA depletion syndrome." (PMID 37085601, 2024). "The Chr17: 62492543G>A POLG2 mutation (R182W p55) was the first homozygous POLG2 mutation identified, and the affected infant presented with liver failure at 3 months of age and subsequently died at 9 months." (PMID 30157269, 2018). "Differential diagnosis should also be considered with other mitochondrial disorders causing liver failure (MPV17, POLG1, POLG2, TFAM, TWNK, TRMU)." (PMID 38756539, 2024). "Furthermore, biallelic mutations in POLG2 cause a severe infancy-onset phenotype referred to as “mitochondrial DNA depletion syndrome” (OMIM #618,528 or #619,425), leading to liver failure and death in infancy." (PMID 37085601, 2024). "Finally, mutations in the POLG2 gene, encoding the accessory dimeric subunit POLG2, enhancing binding to DNA, cause adult-onset dominant PEO although we have recently found a homozygous POLG2 gene mutation causing fatal infantile hepatic failure with mtDNA depletion." (PMID 31718067, 2019).
Parkinsonism (4 papers, 2017 to 2025). Characteristic neurologic anomaly resulting from degeneration of dopamine-generating cells in the substantia nigra, a region of the midbrain, characterized clinically by shaking, rigidity, slowness of movement and difficulty with walking and gait. "This work extends the clinical spectrum of POLG2 deficiency to include an overwhelming, adult‐onset neurological syndrome that includes cerebellar syndrome, peripheral neuropathy, tremor, and parkinsonism." (PMID 28078310, 2017). "Moreover, POLG2 mutations manifested with parkinsonism in three individuals from the same Belgian pedigree and one additional independent female patient, and “extrapyramidal signs” were reported in two, and “pyramidal signs” in four individuals from a recently published family." (PMID 37085601, 2024).
mitochondrial myopathies (2 papers, 2020 to 2024). "Here, we present a novel phenotype in an already reported heterozygous POLG2 mutation with the clinical leading symptom of camptocormia, extending the phenotypic spectrum of POLG2 related mitochondrial myopathies." (PMID 31991853, 2020). "Until now, camptocormia has not been described in the phenotypic spectrum of mitochondrial myopathies caused by POLG2 mutations." (PMID 31991853, 2020).
Sensory neuropathy (2 papers, 2017 to 2018). Peripheral neuropathy affecting the sensory nerves. "We identified 2 heterozygous variants in POLG2 in a 38 year-old patient (N°35) presenting with sensory neuropathy and multiple mtDNA deletions." (PMID 29625556, 2018).
autosomal dominant progressive external ophthalmoplegia (1 paper, 2024). Autosomal dominant form of progressive external ophthalmoplegia. "A single mutation, G451E substitution in POLG2, is not involved in p55 dimerization, resulting in a late onset of adPEO (autosomal dominant progressive external ophthalmoplegia) and COX (cytochrome c oxidase) deficient muscle fibers." (PMID 38598542, 2024).
benign prostatic hyperplasia (1 paper, 2024). A non-cancerous nodular enlargement of the prostate gland. "POLG2 over-expression was observed in PRAD versus corresponding benign prostatic hyperplasia tissues." (PMID 38598542, 2024).
bladder cancer (1 paper, 2024). "Polymorphisms in POLG2 gene thought to be genetically associated with aggressive bladder cancer in Japanese men." (PMID 39023752, 2024).
calcification (1 paper, 2019). Process by which organic tissue becomes hardened by the physiologic deposit of calcium salts. "Further analysis of all 85 G2 mice and 138 G3 mice revealed that 84% of G2 mice with renal calcification, and 71% of G3 mice with renal calcification had the Tyr265Stop Polg2 mutation, indicating that the mutation, which co‐segregates with the phenotype, had a reduced penetrance." (PMID 30395686, 2019). "Thus, our studies have identified a mutant mouse model for inherited renal calcification associated with a Polg2 nonsense mutation." (PMID 30395686, 2019).
Camptocormia (1 paper, 2020). An abnormal forward-flexed posture e.g. forward flexion of the spine, which is noticeable when standing or walking but disappears when lying down. "This is the first report on a POLG2 mutation leading to camptocormia as the main clinical phenotype, extending the phenotypic spectrum of POLG2 associated diseases." (PMID 31991853, 2020). "However, in none of the reported POLG2 mutations, camptocormia has been described." (PMID 31991853, 2020).
Fulminant hepatic failure (1 paper, 2020). Hepatic failure refers to the inability of the liver to perform its normal synthetic and metabolic functions, which can result in coagulopathy and alteration in the mental status of a previously healthy individual. "An infant with fulminant hepatic failure and mitochondrial DNA depletion caused by a homozygous POLG2 missense variant has been reported." (PMID 31991853, 2020).
melanoma (1 paper, 2025). A malignant, usually aggressive tumor composed of atypical, neoplastic melanocytes. "In GSE46517, IFFO1, ANKRD10, CLPB, TCAP, and POLG2 displayed high expression, but the expression levels of CHMP4A, ZDHHC11, and ANKMY1 were low in the melanoma group." (PMID 40909968, 2025).
osteosarcoma (1 paper, 2022). A usually aggressive malignant bone-forming mesenchymal neoplasm, predominantly affecting adolescents and young adults. "To this end, we evaluated the viability of the human osteosarcoma 143B cells after inactivating TFAM, POLRMT, TFB2M, POLG, POLG2, or SSBP1 with CRISPR-Cas9." (PMID 35883613, 2022).
prostate carcinoma (1 paper, 2024). A carcinoma that arises from epithelial cells of the prostate gland. "Prior studies have focused on the single nucleotide polymorphism (SNP) of POLG2 gene, which is reportedly responsible for encoding mitochondrial DNA genes and is implicated in the material and energy metabolism of tumor cells, whereas its function in prostate cancer has been elusive." (PMID 38598542, 2024). "In summary, our findings indicate that over-expressed POLG2 renders poor prognosis in advanced prostate cancer." (PMID 38598542, 2024). "Meanwhile, the results of IHC in HPA and tissue array further confirmed that the expression of POLG2 was higher in cancerous tissue compared with normal adjacent tissues (p = 0.033) and POLG2 expression was related to malignancy of prostate cancer (p = 0.038)." (PMID 38598542, 2024). "Multivariate analysis showed that POLG2 might be an independent prognostic factor of prostate cancer." (PMID 38598542, 2024). "In order to understand whether POLG2 knockdown could affect the invasion of prostate cancer and exclude chronic compensatory response, we conducted cell invasion assay between PC-3, 22RV1 stable cell lines." (PMID 38598542, 2024). "The results suggested evident proliferative inhibition of POLG2 knockdown in prostate cancer cells." (PMID 38598542, 2024). "Furthermore, we verified that POLG2 knockdown had an inhibitory effect on mitochondrial function, proliferation, cell motility, and invasion, we affirmed POLG2 could affect the prognosis of advanced prostate cancer via EMT." (PMID 38598542, 2024).
ptosis (1 paper, 2017). The drooping of the upper eyelid. "This reduction in POLG2 expression was associated with late‐onset ptosis and myopathy." (PMID 28078310, 2017).
mitochondrial disease (9 papers, 2010 to 2024). "Mutations in human POLG or POLG2 lead to a group of multi-organ mitochondrial diseases with Mendelian inheritance, collectively named POLG-related disorders, characterized by multiple deletions and/or depletion of mtDNA." (PMID 38643274, 2024). "Moreover, it has recently been published that POLG2 is also able to directly bind to DNA, providing new insights into molecular defects associated with POLG2 disruption in mitochondrial disease." (PMID 38643274, 2024). "Thus the c.390-2A > C splice acceptor variant in POLG2 we identified is consistent with previous POLG2 pathogenic variants responsible for mtDNA deletions and late-onset mitochondrial disease." (PMID 29625556, 2018). "Thus, the c.970‐1G>C splice acceptor variant in POLG2 we identified that causes reduction in POLG2 expression is consistent with previous POLG2 mutations causing mtDNA deletions and late‐onset mitochondrial disease." (PMID 28078310, 2017). "The majority of the core proteins of the mtDNA replication and expression machinery are dedicated mitochondrial proteins, with pathological variants resulting solely in mitochondrial disease phenotypes, including POLG, POLG2, TWINKLE, MGME1 and POLRMT." (PMID 37013609, 2023). "With the exception of SSBP1, a key component of the mitochondrial replication fork, to date, all nuclear genes directly involved in mtDNA replication (POLG, POLG2, TWINKLE, RNASEH1, DNA2, MGME1) have been associated with mitochondrial disease, mtDNA depletion, and/or mtDNA deletion." (PMID 31550237, 2020). "Probands from two families with probable mitochondrial disease were examined clinically, muscle and buccal epithelial DNA were analyzed for mtDNA deletions, and the POLG1, POLG2, ANT1 and Twinkle genes were sequenced." (PMID 20438629, 2010).
cancer (2 papers, 2023 to 2024). A tumor composed of atypical neoplastic, often pleomorphic cells that invade other tissues. "The cancer tissues with the variant allele (TC + CC) in POLG2 contained 1.6 times more mitochondrial DNA (P < 0.01) than those with wild-type cancer tissues." (PMID 38598542, 2024). "Results showed that POLG2 was over-expressed in most cancer types, and the over-expression of POLG2 was correlated with PCa progression and suggested poor OS (Overall Survival) and PFI (Progress Free Interval)." (PMID 38598542, 2024). "EPHX2, ACSF2, CYP27A1, ACSS1, and ALDH1L1 showed hypermethylation in several types of human cancer; on the contrary, AKR1B10, POLG2, NDUFB8, ACACB, and MRPS22 consistently showed hypomethylation in several types of human cancer." (PMID 37223030, 2023).
tumor (2 papers, 2018 to 2024). "Epithelial-mesenchymal transition (EMT) is an essential process and is often involved in tumor metastasis during development; Gene Set Enrichment Analysis (GSEA) revealed that high expression of POLG2 was related to EMT progression." (PMID 38598542, 2024). "The mtDNA replication factors POLG2, TOP1 MT and TWNK were also found to be down-regulated in the GBM50 and GBM3 tumours." (PMID 30208958, 2018).
metabolic disorders (1 paper, 2023). "Changes and mutations of POLG2 have been correlated with mitochondrial-associated metabolic disorders, including T2D." (PMID 38027148, 2023).
myopathy (1 paper, 2017). A disease of the muscle in which the muscle fibers do not function properly. "Like POLG2 mutations, other genetic causes of primary multiple mtDNA deletion syndromes most often present as adPEO with myopathy, but also manifest a broad range of age of onset with variable phenotypes and expressivity." (PMID 28078310, 2017).
POLG2 also shares sentences with these, for which no sentence is quoted: peripheral neuropathy (3 papers); cerebellar ataxia (2); mitochondrial DNA depletion syndrome (2); neuropathy (2); Obesity (2); Tremor (2); acute myeloid leukaemia (1); ad (1); cholestasis (1); cognitive decline (1); Dystonia (1); epilepsy (1); Hypercalciuria (1); Insulin resistance (1); movement disorder (1); nephrocalcinosis (1); nephrolithiasis (1); neurological diseases (1); Onset (1); ophthalmoplegia (1); premature ovarian failure (1); retinitis pigmentosa (1).